RN7SL606P (RNA, 7SL, cytoplasmic 606, pseudogene)
Gene: Miscellaneous RNA gene on chromosome 17 (60,696,313 to 60,696,605, forward strand). Ensembl gene ENSG00000239932.
Homologues: Orthologues: chimpanzee Metazoa_SRP (99% identical), macaque Metazoa_SRP (91% identical). Paralogues in human: RN7SL1 (85% identical), RN7SL2 (85% identical), RN7SL3 (84% identical), RN7SL230P (82% identical), RN7SL45P (82% identical), RN7SL665P (82% identical), RN7SL126P (81% identical), RN7SL130P (81% identical), RN7SL278P (81% identical), RN7SL448P (81% identical), RN7SL464P (81% identical), RN7SL597P (81% identical), and 705 more.